EIF4A1 (eukaryotic translation initiation factor 4A1)
Diseases named in the same sentence as EIF4A1 in open-access papers (continued):
Sharing a sentence is not in itself a finding about the gene and the disease.
cancer (continued). "Collectively, these data indicate that IBTK plays critical roles in promoting oncogene expression and cancer cell malignancy by upregulating eIF4A1 activity." (PMID 38738857, 2024). "Of particular interest, eIF4A1 is a crucial subunit of the eIF4F complex and a promising therapeutic target for cancer." (PMID 38738857, 2024). "EIF4A1 has been demonstrated to be aberrantly regulated in many types of cancers, such as CRC, gastric cancer, breast cancer, cervical cancer, and hepatocellular carcinoma." (PMID 38023215, 2023). "Given the importance of the translation process of mRNAs in cancer development, several small molecules have been shown to have antitumor activity by acting on or inhibiting eIF4A1." (PMID 38028556, 2023). "And we propose eukaryotic translation initiation factor 4A1 as a target and biomarker for cancer prognosis, diagnosis and treatment." (PMID 38028556, 2023). "Söylemez and his coworkers showed that compared with non-cancer subjects, EIF4A1 mRNA expression was decreased in the tumor tissues from CRC patients of stage I, III, and IV, but increased in stage II." (PMID 38023215, 2023). "With the understanding and deepening of the regulatory mechanism of eIF4A1, we found that eIF4A1 can be one of the potential points of action and biomarkers for cancer diagnosis and therapy." (PMID 38028556, 2023). "Our findings confirm the protein functional role and regulatory mechanism of eukaryotic translation initiation factor 4A1 protein in human cancer." (PMID 38028556, 2023). "Recent studies have shown that the natural marine products cycloartenol and cycloterpenol can inhibit eIF4A1 and offer promising prospects for cancer therapy." (PMID 38028556, 2023). "The increased expression of EIF4A1 was connected with higher sensitivity to cladribine in cancer cells." (PMID 37089261, 2023). "The eukaryotic translation initiation factor 4A1 (EIF4A1) was an important regulator of many cancers." (PMID 35435117, 2022). "The results showed that EIF4A1 and its regulated gene sets were mainly involved in cell cycle progression and cancer proliferation." (PMID 36101357, 2022). "Eif4a1 is an eukaryotic translation initiation factor that promotes cell growth and cancer progression." (PMID 36100596, 2022). "To elucidate the signaling network of EIF4A1 in cancer development, we extracted the gene sets with a positive correlation to EIF4A1 in LUAD." (PMID 36101357, 2022). "Our results also imply that inhibiting the interaction between SRSF3 and eIF4A1 is a possible therapeutic approach for inducing p21-dependent cellular senescence in cancer cells." (PMID 36344491, 2022). "The UALCAN results indicated that EIF4A1 protein levels were upregulated in ccRCC, which also significantly and positively correlated to cancer stages and to tumor grades of ccRCC." (PMID 35592316, 2022). "Given the importance of mRNA translation in the development of cancer, several small molecules have been shown to possess antitumor activities by targeting or inhibiting eIF4A1." (PMID 34869305, 2021). "Previous studies have shown that the natural marine product, elatol, inhibits eIF4A1, providing a highly promising target for cancer therapy." (PMID 34869305, 2021). "Several efforts have since explored inhibiting the activities of eIF4F to block ribosome recruitment in cancer, and impeding eIF4A1 function with rocaglates has emerged as a promising avenue." (PMID 34531456, 2021). "The eIF4A1 expression was positively correlated with lymph node metastasis which is a major mechanism of cancer cell metastasis." (PMID 34906136, 2021). "CRISPR/Cas9 editing has provided strong evidence that anti-cancer activities of flavaglines are mediated via eIF4A1." (PMID 32924027, 2020). "There is increasing interest in targeting eIF4A1 therapeutically in cancer, thus understanding how this protein leads to the selective re-programming of the translational landscape is critical." (PMID 31888698, 2019).
cancer (continued). "Recent studies have highlighted the importance of eIF4A activity in cancer, and while eIF4A1 expression correlates with cell proliferation, that of eIF4A2 does not." (PMID 31791371, 2019). "eIF4A1 levels are increased in several cancers and predict poor prognosis, whilst high eIF4A2 levels are linked to better survival rates." (PMID 31180491, 2019). "Alterations in the expression of several eIF4A1 activity-modulating proteins have been observed in many cancers." (PMID 25611378, 2015). "eIF4A1 was suggested to be a potential target for developing new anti-cancer and anti-inflammatory drugs given evidence of cross-talk between translation and the inflammatory response." (PMID 22247778, 2012). "As eIF4A1 has been identified as a potential prognostic marker in various cancers, these antibodies could be employed in immunohistochemical analyses of patient tissues to assess eIF4A1 expression patterns in tumor progression and treatment response." (PMID 41299109, 2025). "Additionally, further research on the roles of eIF4A1 and eIF4A2 in cancer development is warranted." (PMID 40423315, 2025). "Since eIF4A1-mediated mRNA translation largely promotes cancer progression, we may have unveiled a novel oncolytic mechanism of NDV that entails the targeted suppression of highly active oncogene expression in tumor cells." (PMID 38377149, 2024). "Finally, the gene expression patterns of cancer cell lines from the Genomics of Drug Sensitivity in Cancer database were combined in order to comprehensively investigate the potential therapeutic benefit of the EIF4A1, EIF4G4, NCBP1, and WDR4 genes." (PMID 36816047, 2023). "Given the significant involvement of CYFIP1 and EIF4A1 in cancer pathogenesis, including their potential roles in invasion and protein translation, targeting these molecules may hold promise as a therapeutic approach for OS." (PMID 37654606, 2023). "Whereas EIF4A1 and EIF4EBP1 are responsible for translation and translation repression, respectively; but with respect to cancer EIF4A1 promotes metastasis, while EIF4EBP1 promotes tumourigenesis when phosphorylated and suppresses tumourigenesis when unphosphorylated." (PMID 37277696, 2023). "Consistent with the results, the GSVA score of genes whose expression was negatively correlated with EIF4A1 was lower in the tumor tissue of LUAD cases with worse clinical outcomes and was strongly associated with the disequilibrium of anti-cancer immunity by recruiting anticancer immune cells." (PMID 36101357, 2022). "Based on the results from the present study, we hypothesize that the dysregulation of EIF4A1 might be involved in the pathophysiology of LUAD development by promoting cancer growth and changing the tumor immune microenvironment." (PMID 36101357, 2022). "The antineoplastic activity of eFT226, an inhibitor of the translation initiation factor eIF4A1, has been reported in a variety of cancer cells, eFT226 recently became the first rocaglate to enter clinical evaluation for advanced solid tumors in humans (ClinicalTrials.gov: NCT04092673)." (PMID 35805935, 2022). "eIF4A1 has also been shown to promote the tumor cell malignant phenotype in breast, oral squamous cell, and cervical cancers." (PMID 34869305, 2021). "eIF4A1 is the major type that participates in the assembly of eIF4F in cancer cells." (PMID 34906136, 2021). "eIF4A2 is a paralogue of eIF4A1 and although the amino acid sequences of both proteins are highly similar they have opposing functions, resulting in contrasting effects of the helicases in cancer." (PMID 31180491, 2019). "Additionally, the ability to differentiate between eIF4A1 and eIF4A2 in tumor versus normal tissues may yield novel insights into their distinct roles in cancer biology." (PMID 41299109, 2025). "Similarly, EIF4A1, a translation initiation factor, may drive tumor proliferation by enhancing oncoprotein synthesis, a mechanism observed in other cancers." (PMID 40709174, 2025).
cancer (continued). "In this study, we showed that full-length eIF4A1 and eIF4A2, sharing exactly 95.3% similarity in amino acid sequences, exhibit different enzymatic properties, which may result in their distinct roles in cancer development." (PMID 40423315, 2025). "Therefore, EIF4A1 has begun to attract attention for cancer therapy." (PMID 33237662, 2021). "Additionally, the differences between eIF4A1 and eIF4A2, which have been underestimated by previous studies, potentially provide an opportunity for developing selective therapeutic interventions that specifically target cancer cells while leaving normal cells intact." (PMID 40423315, 2025). "EIF4A1 and cofactors EIF4B and EIF4H have been well characterised in cancers, including B cell malignancies, for their ability to promote the translation of oncogenes with structured 5′ untranslated regions." (PMID 38011999, 2024). "Given the crucial role of eIF4A1 in cancer biology, we conducted additional investigations to determine if IBTK promotes neoplastic phenotypes in cancer cells." (PMID 38738857, 2024). "The ATP-dependent RNA helicases eIF4A1 plays a crucial role in various cancers in humans The expression level of eIF4A1 varies in different types of malignant tumors." (PMID 38028556, 2023). "EIF4A1 is a necessary component of EIF4F, which was considered a direct connection between essential steps in cancer development and translation initiation." (PMID 37089261, 2023). "In addition, this review also discusses the role of eIF4A1 in the process of tumor proliferation and metastasis, and existing inhibitors, suggests the possibility of using them as a potential point of action and biomarker for cancer diagnosis, treatment and prognosis." (PMID 38028556, 2023). "To facilitate the clinical transformation of the five genes model, we further identified FDA-approved sensitive drugs that express high levels of CYFIP2, EIF4A1, NUDT1, NUDT4, and NUDT10 in multiple cancer cell types." (PMID 37089261, 2023). "For the first time, our paper describes EIF4A1, CLIC1, PRDX6, CLIC4, ENO1, ANXA4, EMD and Ku70 in relation to EEC, although their role is well established in other cancers." (PMID 22415234, 2012). "Lastly, while our findings on EIF4A1 and DDX3X remain robust and underscore the potential importance of these RNA helicases in virus-positive tumors, they are derived from a limited number of cancer types." (PMID 40595559, 2025). "Other fusion partners frequently found among this set that may be potentially relevant to pediatric cancer include PTMA (seven fusions), EIF4A1 and the EIF4A1 locus-derived RP11-186B7.4 (seven unique fusions), and SEPT14 (three fusions)." (PMID 37323575, 2023). "Normally (for normal expression in cancer cells), PDCD4 inhibits the interaction between EIF4A1 and EIF4G, which reduces the helicase activity of EIF4A1, thereby disrupting translation and resulting in impaired growth factor formation, growth stimulation genes, and proto-oncogenes." (PMID 36768298, 2023). "Additionally, analysis of drug sensitivity indicated that EIF3D, EIF4A1, and LARP1 expressed by cancer cells greatly influenced the sensitivity of the cells to chemotherapy." (PMID 35602299, 2022). "The expression levels of EIF4A1 were tumor grade-dependent (right two panels) but not concordant with individual cancer stages." (PMID 36101357, 2022). "Importantly, we observed that c-MYC expression was positively correlated with eIF4A1 expression in PDAC and across various cancer types (n = 44, r = 0.5041, P = 0.0005, Spearman correlation)." (PMID 34906136, 2021). "EIF4A1 is a helicase that unwinds the 5′UTR of mRNA for the initiation of protein translation, and is involved in embryogenesis and certain disease conditions, such as cancer." (PMID 28911096, 2017). "Moreover, CRISPR/Cas9-mediated KO or shRNA-mediated KD of IBTK in multiple cancer cell lines did not alter the levels of eIF4A1/2/3." (PMID 38738857, 2024).
cancer (continued). "Interestingly, eIF4A1, but not eIF4A2, is a common essential gene in most cancer cell lines in CRISPR knockout screens." (PMID 37874652, 2023). "EIF4A1 has been reported to directly determine the selective translation of oncoproteins, such as myc, myb, notch, cdk6, bcl-2 and ROCK1, which are critical regulators contributing to cancer survival, proliferation, migration, invasion, metastasis and chemoresistance." (PMID 36101357, 2022).
tumor (53 papers, 2010 to 2026). "In mouse lymphoma models, the loss of a single copy of Eif4a1 or Eif4e by the tumour leads to improved survival of the host." (PMID 38011999, 2024). "PDCD4, the other gene region that was identified in the AA stratum, is a tumor suppressor gene that encodes a protein that binds to eukaryotic translation initiation factor 4A1." (PMID 38162683, 2023). "EIF4A1 snoRT levels in tumor specimens also proved to be strongly associated to patients’ specific survival, mirroring the ER and PGR status." (PMID 35996163, 2022). "Filtering yielded 46 likely somatic mutations in the tumor, of which 7 (affecting EIF4A1, EPHA3, FAF1, IPO8, KIAA1377, LIMCH1, and NIPBL) were confirmed in the RNASeq results." (PMID 25861239, 2015). "We hypothesized that the varying effects of BLF1 in tumor and healthy cells may be caused by its differential effects on eIF4A1 and eIF4A2." (PMID 40423315, 2025). "Moreover, accumulating studies have linked EIF4A1 to malignant phenotypes of tumor cells and tumor-specific survival." (PMID 37089261, 2023). "The translation regulator EIF4A1, enriched in ICCs of both clusters, emerges as a therapeutic target, as its inhibition with eFT226 significantly reduces tumor growth in an ICC PDX model." (PMID 41872184, 2026). "Consistent with this, spatial transcriptomic profiling revealed stronger expression of eIF4A1 and eIF4G1 in the metastatic sample than in the primary tumor sample." (PMID 41279557, 2025). "Subsequent univariate Cox and LASSO regression analyses narrowed the selection to five key genes—GGT6, HAO2, SLPI, MELK, and EIF4A1—whose expression patterns correlated strongly with tumor grade, clinical stage, and metastatic status." (PMID 40709174, 2025). "Based on existing studies, both MELK and EIF4A1 are highly expressed in tumor cells, and high EIF4A1 expression has been confirmed to correlate with poor patient prognosis." (PMID 40709174, 2025). "Inhibits protein synthesis by interaction between EIF4A1.Involved in apoptosis and acts as tumor suppressor protein." (PMID 41250600, 2025). "TEM images using immunogold staining for eIF4E and eIF4A1 confirmed the presence of these proteins within tumor cells derived EVs." (PMID 40820860, 2025). "PHGDH also interacts with the translation initiation factors eIF4E and eIF4A1 to promote translation initiation in the cytoplasm, thereby accelerating tumour development." (PMID 38577610, 2024). "Using qRT-PCR analyses further showed increased expression of Xpo1, Rpl12, Rps16, and Eif4a1 in RNA samples from primary prostate and lung metastatic tumor cells of TripleTg mice in comparison to those from PCa tissues of DoubleTg mice." (PMID 38336745, 2024). "eIF4A1 is frequently a target of various microRNAs (miRNAs) or LncRNAs and plays a key role in tumor cell proliferation, invasion and metastasis." (PMID 38028556, 2023). "Most importantly, we construct tissue microarrays from 26 tumor specimens and 20 normal specimens, and further confirm that EIF4A1 and NCBP2 are associated with tumor progression and Gleason score." (PMID 36810782, 2023). "Recently, in a study on brain gliomas and endometrial cancer and human cytomegalovirus, there were also showing that eIF4A1 has significantly higher expression levels in different tumors and functions as a tumor promoter." (PMID 38028556, 2023). "Here, we investigated the pathogenetic and therapeutic role of eukaryotic initiation factor 4A1 (eIF4A1) in this tumor type." (PMID 36768380, 2023). "The fact that eIF4A1 was consistently upregulated in HCC in comparison with adjacent non-tumor liver tissue and the magnitude of this change was negatively correlated with the prognosis of HCC patients supports a role of eIF4A1 in HCC malignancy." (PMID 36768380, 2023). "Our results showed that NCBP2 and EIF4A1 proteins were significantly highly expressed in tumor tissue and that the protein expression ofNCBP2 andEIF4A1 increased significantly with an increasing Gleason score." (PMID 36810782, 2023).